SNORD116-5 (small nucleolar RNA, C/D box 116-5)
Synonyms: HBII-85-5
Gene: Small nucleolar RNA gene on chromosome 15 (25,062,333 to 25,062,427, forward strand). Ensembl gene ENSG00000207191.
Gene Ontology:
Biological process: RNA processing
Cellular component: nucleolus
Homologues: Orthologues: macaque SNORD116 (97% identical), rabbit SNORD116 (89% identical), rabbit SNORD116 (88% identical), rabbit SNORD116 (87% identical), rabbit SNORD116 (86% identical), rabbit SNORD116 (83% identical), rabbit SNORD116 (78% identical), rabbit SNORD116 (77% identical). Paralogues in human: SNORD116-7 (100% identical), SNORD116-3 (99% identical), SNORD116-9 (99% identical), SNORD116-8 (97% identical), SNORD116-1 (96% identical), SNORD116-4 (96% identical), SNORD116-2 (95% identical), SNORD116-6 (94% identical), SNORD116-14 (86% identical), SNORD116-15 (86% identical), SNORD116-17 (85% identical), SNORD116-19 (85% identical), and 20 more.